TRBV12-3 (T cell receptor beta variable 12-3)
Description:
V region of the variable domain of T cell receptor (TR) beta chain that participates in the antigen recognition. Alpha-beta T cell receptors are antigen specific receptors which are essential to the immune response and are present on the cell surface of T lymphocytes. Recognize peptide-major histocompatibility (MH) (pMH) complexes that are displayed by antigen presenting cells (APC), a prerequisite for efficient T cell adaptive immunity against pathogens. Binding of alpha-beta TR to pMH complex initiates TR-CD3 clustering on the cell surface and intracellular activation of LCK that phosphorylates the ITAM motifs of CD3G, CD3D, CD3E and CD247 enabling the recruitment of ZAP70. In turn ZAP70 phosphorylates LAT, which recruits numerous signaling molecules to form the LAT signalosome. The LAT signalosome propagates signal branching to three major signaling pathways, the calcium, the mitogen-activated protein kinase (MAPK) kinase and the nuclear factor NF-kappa-B (NF-kB) pathways, leading to the mobilization of transcription factors that are critical for gene expression and essential for T cell growth and differentiation. The T cell repertoire is generated in the thymus, by V-(D)-J rearrangement. This repertoire is then shaped by intrathymic selection events to generate a peripheral T cell pool of self-MH restricted, non-autoaggressive T cells. Post-thymic interaction of alpha-beta TR with the pMH complexes shapes TR structural and functional avidity.
Synonyms: TCRBV12S3; TCRBV8S1; TRBV123
Tractability: Antibody: its Gene Ontology location is reachable by antibodies, with high confidence; UniProt places it where antibodies can reach, with medium confidence; UniProt predicts a signal peptide or a membrane-spanning region. PROTAC: ubiquitination databases record sites on it.
Gene: T-cell receptor variable (V) gene on chromosome 7 (142,560,423 to 142,560,931, forward strand). Ensembl gene ENSG00000274752.
Subcellular location: Cell membrane
Pathways (Reactome):
Immune System: Co-inhibition by PD-1; Downstream TCR signaling; Generation of second messenger molecules; Immunoregulatory interactions between a Lymphoid and a non-Lymphoid cell; Phosphorylation of CD3 and TCR zeta chains; Translocation of ZAP-70 to Immunological synapse
Gene Ontology:
Molecular function: MHC protein binding; peptide antigen binding
Biological process: cell surface receptor signaling pathway; immune response
Cellular component: plasma membrane
Homologues: Orthologues: mouse Trbv15 (63% identical). Paralogues in human: TRBV12-4 (97% identical), TRBV12-5 (70% identical), TRBV7-6 (57% identical), TRBV7-2 (56% identical), TRBV7-7 (56% identical), TRBV17 (55% identical), TRBV7-3 (55% identical), TRBV7-9 (54% identical), TRBV14 (53% identical), TRBV7-4 (53% identical), TRBV11-2 (52% identical), TRBV11-3 (52% identical), and 39 more.